FREM1 (FRAS1 related extracellular matrix 1)
Description:
Extracellular matrix protein that plays a role in epidermal differentiation and is required for epidermal adhesion during embryonic development.
Synonyms: C9orf143; C9orf145; C9orf154; FLJ25461; DKFZp686M16108; TILRR; BNAR; MOTA; TRIGNO2
Tractability: Antibody: UniProt places it where antibodies can reach, with medium confidence; UniProt predicts a signal peptide or a membrane-spanning region; its Gene Ontology location is reachable by antibodies, with medium confidence. PROTAC: ubiquitination databases record sites on it.
Gene: Protein-coding gene on chromosome 9 (14,734,671 to 14,910,995, reverse strand). Ensembl gene ENSG00000164946.
Subcellular location: Secreted, extracellular space, extracellular matrix, basement membrane
Gene Ontology:
Molecular function: protein binding
Biological process: craniofacial suture morphogenesis; cell-matrix adhesion; epithelial structure maintenance; cell communication
Cellular component: extracellular matrix; basement membrane; membrane
Genetic constraint (gnomAD): Loss-of-function variants: 151 observed, 149.34 expected, observed/expected ratio (o/e) 1.01, 90% interval 0.88 to 1.16. The synonymous counts are far from expectation, so gnomAD's model fits this gene poorly and the ratio says little. Missense variants: 2,776 observed, 2,204.9 expected, observed/expected ratio (o/e) 1.26, 90% interval 1.22 to 1.3. Synonymous variants: 987 observed, 833.35 expected, observed/expected ratio (o/e) 1.18, 90% interval 1.12 to 1.25.
Homologues: Orthologues: chimpanzee FREM1 (99% identical), macaque FREM1 (96% identical), pig FREM1 (84% identical), rabbit FREM1 (84% identical), dog FREM1 (84% identical), guinea pig FREM1 (83% identical), mouse Frem1 (78% identical), rat Frem1 (77% identical), tropical clawed frog frem1 (60% identical), zebrafish frem1a (52% identical). Paralogues in human: FREM2 (32% identical), FREM3 (27% identical), FRAS1 (25% identical), ADGRV1 (14% identical), SLC8A1 (8% identical), SLC8A3 (7% identical), SLC8A2 (7% identical).
Diseases named in the same sentence as FREM1 in open-access papers:
FREM1 is named in the same sentence as 60 diseases in open-access papers, as found by Europe PMC text mining. Sharing a sentence is not in itself a finding about the gene and the disease. The quoted sentences say what the papers report.
breast cancer (13 papers, 2020 to 2025). A primary or metastatic malignant neoplasm involving the breast. "Conversely, increased expression of FREM1 in breast cancer is associated with a favorable prognosis and high-level immune infiltration status." (PMID 34439271, 2021). "To understand the underlying mechanism of FREM1 in breast cancer, we analyzed differentially expressed data from the 50 highest and 50 lowest FREM1-expressing tumor tissue samples." (PMID 33031059, 2020). "Upon overexpression of FREM1 in breast cancer cell lines, as confirmed by both qPCR and Western blot, we observed a significant reduction in tumor cell proliferation, migration, and invasion." (PMID 41324818, 2025). "In this study, we integrated bioinformatics analyses with experimental validation to investigate the role of FREM1 as a prognostic biomarker and therapeutic target in breast cancer by developing a BM-related gene signature." (PMID 41324818, 2025). "Collectively, these data underscore FREM1's multifaceted role in breast cancer biology and highlight the advancements contributed by our integrated experimental approach." (PMID 41324818, 2025). "To further investigate its functional significance, we established a ​​FREM1-overexpressing breast cancer cell model​​ and confirmed successful upregulation of both mRNA and protein levels." (PMID 41324818, 2025). "Functional assays consistently demonstrated that FREM1 overexpression significantly suppressed the malignant behavior of breast cancer cells." (PMID 41324818, 2025). "Collectively, these data position FREM1 as a key regulator of breast cancer progression, with both prognostic implications and potential therapeutic relevance for overcoming tumor immunosuppression." (PMID 41324818, 2025). "Experimental validation in breast cancer cell lines showed that FREM1 expression was significantly lower in tumor cells compared to normal cells." (PMID 41324818, 2025). "Our study demonstrated that FREM1 is downregulated in breast cancer tissues compared to normal controls, correlates with poor clinical outcomes and an immunosuppressive tumor microenvironment, and that its overexpression can suppress tumor malignant behaviors." (PMID 41324818, 2025). "These experimental findings are supported by accumulating clinical evidence establishing FREM1 as a tumor suppressor in breast cancer." (PMID 41324818, 2025). "Another study demonstrated that elevated FREM1 expression in breast cancer is a marker of favorable prognosis and high levels of immune infiltration." (PMID 37178414, 2023). "A study in breast cancer showed that the expression of FREM1 was dramatically decreased, which correlated with a lower overall and recurrence-free survival." (PMID 35909471, 2022). "Recently, many studies have shown that FREM1 can be used as a new therapeutic target and prognostic marker for breast cancer and the increase in its expression is related to the high level of infiltration of anti-tumor immune cells." (PMID 36186476, 2022). "The prognostic result of FREM1 is consistent with that in all breast cancer, while low STAC2 expression predicted high OS (p < 0.05) in all breast cancer." (PMID 33644115, 2021). "Further studies are needed to determine the exact roles prognostic values of STAC2 and FREM1 in breast cancer and LumB-subtype breast cancer." (PMID 33644115, 2021). "Among the 47 breast cancer samples, FREM1 staining was high in 4 samples (8.5%), moderate in 22 samples (46.8%) and weak or undetectable in 21 samples (44.7%)." (PMID 33031059, 2020). "FREM1 staining in human primary breast cancer was scored as follows: +++, high; ++, moderate; +, weak; −, negative." (PMID 33031059, 2020). "Downregulation of FREM1 gene expression was found in breast cancer, ovarian cancer and pancreatic cancer tissues." (PMID 33031059, 2020). "FREM1 expression in breast cancer was further investigated using TCGA and Gene Expression Omnibus (GEO) data." (PMID 33031059, 2020).
breast cancer (continued). "Moreover, while we identified FREM1 as a potential tumor suppressor through in vitro experiments, the functional roles of other signature genes in breast cancer progression remain to be fully elucidated." (PMID 41324818, 2025). "This dual function supports the notion that FREM1 may serve as both a stromal biomarker and a potential therapeutic target in breast cancer progression, with implications for both tumor structure and immune modulation." (PMID 41324818, 2025). "FREM1 may be a potential candidate for immunotherapy targets in breast cancer and may be used as a prognostic marker for DFS." (PMID 33644115, 2021). "FREM1 has been authenticated as an immune-related gene which may be a potential target for immunotherapy in breast cancer and clear cell renal cell carcinoma." (PMID 33274204, 2020). "Thus, FREM1 downregulation in breast cancer tissue, especially in HER2-enriched samples, was correlated with shorter survival times." (PMID 33031059, 2020). "We expanded our analysis of FREM1 expression to various subtypes of breast cancer." (PMID 33031059, 2020). "TILRR is the dominant isoform of FREM1 expressed in breast cancer tissues." (PMID 33031059, 2020). "Notably, our findings align conceptually with a pivotal prior study, which similarly reported decreased FREM1 expression in breast cancer tissues relative to normal controls and identified a correlation between low FREM1 levels and unfavorable prognosis, as well as enriched immune cell infiltration." (PMID 41324818, 2025). "However, the expression of FREM1 in CRC differs from that in breast cancer." (PMID 35909471, 2022). "Hence, FREM1 expression is downregulated in breast cancer tissue." (PMID 33031059, 2020). "To functionally characterize FREM1, we performed in vitro studies using triple-negative MDA-MB-231 breast cancer cells." (PMID 41324818, 2025). "Our results showed that STAC2 and FREM1 were specifically downregulated and their low expressions predicted low RFS and OS (p < 0.05) in LumB-subtype breast cancer." (PMID 33644115, 2021). "In the selected key specific DEGs for LumB-subtype breast cancer, the expression of CNTD2, NEURL, STAC2, AKR1C2, IL6, FREM1, and HOXA4 were significantly correlated with the prognostic survival of the patients." (PMID 33644115, 2021). "We further analyzed TGCA data to determine if there is a relationship between FREM1 expression and overall survival (OS) or disease-free survival (DFS) in breast cancer patients." (PMID 33031059, 2020). "The protein expression identity of FREM1 and TILRR was verified using four paired breast cancer tissues (sample numbers: 160, 172, 109 and 164)." (PMID 33031059, 2020). "CNTD2, NEURL, STAC2, IL6, FREM1, and HOXA4 may be involved in recurrence of LumB-subtype breast cancer." (PMID 33644115, 2021). "In general, the analytical data suggest that STAC2, FREM1, and AKR1C2 may be involved in the tumorigenesis to improve OS of patients with LumB-subtype breast cancer." (PMID 33644115, 2021). "Thus, FREM1 may play the similar roles and prognostic values, whereas STAC2 may play different roles and prognostic values in breast cancer and LumB-subtype breast cancer." (PMID 33644115, 2021). "Thus, we used the TIMER database to evaluate the correlation between FREM1 mRNA expression and six different infiltrating immune cell types (B cells, CD8+ T cells, CD4+ T cells, macrophages, neutrophils and dendritic cells) in different subtypes of breast cancer." (PMID 33031059, 2020).
Fraser syndrome (12 papers, 2010 to 2025). Fraser syndrome is a rare clinical entity including as main characteristics cryptophthalmos and syndactyly. "Fraser syndrome in humans results if any of the core members of the Fraser complex (Fras1, Frem1, Frem2) are mutated." (PMID 37047755, 2023). "We propose that loss of FREM1 function promotes epidermal blistering in Fraser syndrome as a consequence of reduced PDGFC activity, in addition to its stabilising role in the basement membrane." (PMID 24046351, 2013). "The spectrum of anorectal anomalies–which can also include anal stenosis, rectal atresia, and imperforate anus–is also similar between individuals with FREM1 deficiency and Fraser syndrome." (PMID 23536828, 2013). "Indeed, loss of Frem1 significantly diminished the expression of nephronectin and loss of nephronectin leads to phenotypes overlapping with Fraser syndrome phenotypes." (PMID 37047755, 2023). "Regarding the PPI network, FREM2 interacts with several proteins known to be associated with Fraser syndrome, such as FRAS1, FREM1, and GRIP1." (PMID 41426592, 2025). "These include FRAS1, FREM1, and GRIP1, which are known to be associated with Fraser syndrome, suggesting a coordinated role in the biological processes underlying this disorder." (PMID 41426592, 2025). "Biallelic variants in FREM2, FREM1, or FRAS1 result in Fraser syndrome (MIM 607830; 608945; 604597), a rare autosomal recessive malformation syndrome characterized by cryptophthalmos, syndactyly, urogenital abnormalities, and dental anomalies." (PMID 37046432, 2023). "Of the candidate genes, four genes (i.e., ITGA8, GRIP1, FREM1, and FREM2) were Fraser syndrome-related genes, encoding proteins that functionally converged on the glial cell-derived neurotrophic factor/RET/bone morphogenic protein (BMP) signaling pathways." (PMID 29197384, 2017). "For example, mutations in the zebrafish orthologues of human FRAS1, FREM1 and FREM2 recapitulate the epidermal blistering of distal appendages seen in Fraser Syndrome." (PMID 24400120, 2014). "Similar multi-organ defects have been reported in humans with GRIP1 mutations consistent with Fraser syndrome, a syndrome found with deletion of specific GRIP1 interacting proteins including Frem1 (Fras1 related extracellular matrix 1) and Fras1 (Fraser syndrome 1)." (PMID 27631377, 2016). "The phenotypes of Fraser syndrome caused by variants in FREM2, FREM1, or FRAS1 are not distinguishable." (PMID 37046432, 2023). "This protein family contains two further members, FREM1 and FREM3, however these have not, so far, been implicated in Fraser Syndrome aetiology." (PMID 20419147, 2010). "By establishing a link between FREM1, PDGFC growth factor activity and the downstream regulation of molecules that shape ECM remodelling, the authors bring to light a novel mechanism for the development of basement membrane fragility and blistering in Fraser syndrome and its related diseases." (PMID 24046351, 2013).
Manitoba oculotrichoanal syndrome (7 papers, 2012 to 2023). "The diagnosis of MOTA syndrome was confirmed by the identification of 2 novel stop-gain mutations in the FREM1 gene." (PMID 33478401, 2021). "In our study, we discovered the first case of MOTA syndrome in the population of China, with 2 novel FRAS1 related extracellular matrix 1 (FREM1) gene stop-gain mutations confirmed by whole exome sequencing." (PMID 33478401, 2021). "In summary, this study extends FREM1 heterogeneity in MOTA syndrome of First Nations ancestry." (PMID 22690109, 2012). "There have been many case reports of MOTA syndrome and BNAR syndrome, which are also related to the FREM1 gene." (PMID 38097983, 2023). "In humans, mutations in FREM1 result in several Mendelian conditions with affected midline or para-midline craniofacial features, including BNAR (bifid nose with or without anorectal and renal anomalies) syndrome, Manitoba oculotrichoanal syndrome, and trigonocephaly." (PMID 28441456, 2017).
trigonocephaly (6 papers, 2011 to 2023). "In this report we provide evidence that mutations in FREM1 can also be associated with trigonocephaly." (PMID 21931569, 2011). "In summary, we provide evidence that FREM1 mutations are associated with trigonocephaly." (PMID 21931569, 2011). "Features of trigonocephaly have also been reported in patients with deletions that lie distal to FREM1, further suggesting that other genes may be involved." (PMID 22768875, 2012). "Furthermore, we present the Frem1 mouse as a new animal model for both trigonocephaly and facial asymmetry." (PMID 21931569, 2011). "According to the literature, CER1 and FREM1 have been suggested as responsible for trigonocephaly, DOCK8 has been proposed as a candidate gene for mental retardation and seizures, FOXD4 has been related to speech and language delay, and DMRT1 may play a role in sex reversal." (PMID 36672887, 2023). "Although CER1 and FREM1 (OMIM# 608944) were suggested as responsible for trigonocephaly, in our patient 8, who had trigonocephaly, the CER1 and FREM1 loci were not part of the deleted 9p region." (PMID 34609792, 2021).
BNAR syndrome (4 papers, 2011 to 2025). "Alterations in FREM1 have been linked to Bifid Nose, Renal Agenesis, and Anorectal Malformations (BNAR) syndrome, a rare autosomal recessive disorder." (PMID 41288877, 2025). "One fetus was diagnosed with BNAR syndrome through an FREM1 variant." (PMID 37535131, 2024).
congenital diaphragmatic hernia (4 papers, 2013 to 2023). A posterolateral defect of the diaphragm that allows passage of abdominal viscera into the thorax, leading to respiratory insufficiency and persistent pulmonary hypertension with high mortality. "A similar constellation of findings–microphthalmia, cryptophthalmos, congenital diaphragmatic hernia, renal agenesis and rectal prolapse–have been described in FREM1-deficient mice." (PMID 23536828, 2013). "In humans, recessive mutations in FREM1 cause eye defects, congenital diaphragmatic hernia, renal anomalies and anorectal malformations including anteriorly placed anus." (PMID 23536828, 2013). "Similarly, recessive mutations in Frem1 have been shown to cause congenital diaphragmatic hernia (CDH) which has not been documented in mice with Fras1, Frem2 or Grip1 mutations." (PMID 23536828, 2013).
craniosynostosis (3 papers, 2011 to 2021). Craniosynostosis is defined as the premature fusion of one or more cranial sutures leading to secondary distortion of skull shape resulting in skull deformities with a variable presentation. "The second publication describes heterozygous FREM1 deletions and 3 missense variants that associate with metopic craniosynostosis as well as documenting the contribution of FREM1 in patterning the murine cranial skeleton." (PMID 22690109, 2012). "Taken together with Frem1 gene and protein expression findings, these data indicate that mutations in FREM1 can give rise to metopic craniosynostosis." (PMID 21931569, 2011). "It is intriguing to speculate that FREM1 could also bind FGFs and that the craniosynostosis associated with a mutation in these repeats arises through altered FGFR activation as a result of increased intrasutural FGF availability or its affinity for their receptors." (PMID 21931569, 2011). "Here, we report genetic variants involving chromosome 9 which involve and interrupt the structure of the FREM1 gene in a large cohort of patients presenting with unisutural metopic craniosynostosis." (PMID 21931569, 2011). "Furthermore, we present Frem1 mutant mice as the first bona fide mouse model of human metopic craniosynostosis and a new model for midfacial hypoplasia." (PMID 21931569, 2011).
cryptophthalmos (3 papers, 2010 to 2013). "Support for the concept of a regulatory variant is provided by the Frem1bfd murine strain, which lacks a coding Frem1 mutation and is believed to have a variant in a control region that causes cryptophthalmos-like phenotypes." (PMID 22690109, 2012). "In this paper, we identify a homozygous Frem1 missense mutation (c.1687A>T, p.Ile563Phe) in an N-ethyl-N-nitrosourea (ENU)-derived mouse strain, crf11, with microphthalmia, cryptophthalmos, renal agenesis and rectal prolapse." (PMID 23536828, 2013). "More recently, homozygous FREM1 mutations were shown in a Middle Eastern sibship to be associated with a bifid nose, anorectal, and renal anomaly phenotype, but which lacked cryptophthalmos, suggesting that FRAS/FREM variants may contribute to a diverse spectrum of related disorders." (PMID 22690109, 2012). "Given the known interactions between these proteins, it is not surprising that FREM1-, FRAS1-, FREM2- and GRIP1-deficient mice have overlapping patterns of defects that include cryptophthalmos and syndactyly–which are likely to be secondary effects of blister formation–and renal agenesis." (PMID 23536828, 2013).